FOXP3 (forkhead box P3)
Diseases named in the same sentence as FOXP3 in open-access papers (continued):
Sharing a sentence is not in itself a finding about the gene and the disease.
osteoarthritis (2 papers, 2016 to 2023). A noninflammatory degenerative joint disease occurring chiefly in older persons, characterized by degeneration of the articular cartilage, hypertrophy of bone at the margins and changes in the synovial membrane. "Earlier research has established a link between the FoxP3/rs3761548 and an elevated risk of severe osteoarthritis in the Turkish population." (PMID 37904681, 2023). "While we believe that we are the first ones to report on this effect in the context of osteoarthritis, these results match with findings from a number of studies that showed that MSCs could induce FoxP3+ Tregs from the CD4+ fraction." (PMID 27516777, 2016).
Osteopenia (2 papers, 2015 to 2025). Osteopenia is a term to define bone density that is not normal but also not as low as osteoporosis. "In this study, we report severe osteopenia in Sf mice subsequent to the action of Foxp3-deficient lymphocytes." (PMID 25880090, 2015). "Thus, our study suggests that Foxp3 deficiency leads to osteopenia owing to dysregulated NF-κB activity and subsequent cytokine-mediated hyper-proliferation of myeloid precursors, and positions the NF-κB pathway as a potential target for therapeutic intervention for this disorder." (PMID 25880090, 2015).
ovarian adenocarcinoma (2 papers, 2025). An adenocarcinoma that arises from the ovary. "This study investigated the antiproliferative, pro-apoptotic, and immunomodulatory effects of Hes and ADR in human ovarian adenocarcinoma cells (SKOV3), focusing on Forkhead box P3 (FOXP3) and epidermal growth factor receptor (EGFR) signaling pathways." (PMID 41301890, 2025).
ovarian endometriosis (2 papers, 2010 to 2023). A non-neoplastic disorder characterized by the growth of endometrial tissue in the ovaries. "For example, the ovarian endometriosis tissue samples were characterized by an over-expression of mRNA for FOXP3 in comparison to normal endometrial tissue." (PMID 20923543, 2010). "We did not observe any differences over the course of the menstrual cycle in the percentage of FOXP3+ positive cells within the subpopulation of CD4+T lymphocytes in ectopic endometrium in the tissue samples from the group of patients with ovarian endometriosis." (PMID 20923543, 2010). "Furthermore, it has been demonstrated that the percentage of FOXP3 positive lymphocytes found within the subpopulation of T cells in the peripheral blood of women suffering from ovarian endometriosis does not differ from that observed in healthy women." (PMID 20923543, 2010).
papilloma (2 papers, 2021 to 2023). A benign epithelial neoplasm that projects above the surrounding epithelial surface and consists of villous or arborescent outgrowths of fibrovascular stroma. "We found Foxp3+ infiltration to be higher in SCCs compared to papillomas and oral epithelium, indicating increased Treg infiltration during malignant progression of oral tumors." (PMID 33806894, 2021). "Interestingly, oral mucosa of mice exposed to 4NQO showed similar counts of Foxp3+ cells as those observed in papillomas, suggesting an early recruitment of Tregs cells during oral carcinogenesis." (PMID 33806894, 2021).
periapical granuloma (2 papers, 2016 to 2021). Chronic nonsuppurative inflammation of periapical tissue resulting from irritation following pulp disease or endodontic treatment. "The methylation level of the FOXP3 gene promoter was the highest in periapical granulomas and apical cysts, negatively correlated with the expression of FOXP3 mRNA." (PMID 34177907, 2021).
pneumococcal infection (2 papers, 2012 to 2021). Infections with bacteria of the species streptococcus pneumoniae. "Blocking the induction of Foxp3+Helios+ Tregs with the short synthetic peptide P17, an inhibitor of TGF-β, impaired resistance to pneumococcal infection and contributed to bacterial dissemination." (PMID 34257746, 2021).
relapsing (2 papers, 2012 to 2015). "Recent studies suggest that the expression of Foxp3 and the numbers of peripheral CD4+CD25+ Foxp3+ T cells are significantly reduced in relapsing-remitting MS patients compared with those in control subjects." (PMID 23284794, 2012).
renal dysfunction (2 papers, 2022 to 2023). "The purpose of our study was to develop a new non-invasive diagnostic tool, based on an accurate analysis of molecular FOXP3 and CTLA-4 mRNA expression pattern in peripheral blood, during the first post-transplant year, capable to predict aTCMR onset, de novo DSA development and renal dysfunction." (PMID 35109826, 2022). "In our longitudinal prospective and case-control study, we examined in peripheral blood the role played by the FOXP3 and CTLA-4 transcripts as possible biomarkers of clinical outcomes, such as aTCMR, de novo DSA development and renal dysfunction." (PMID 35109826, 2022).
retinal degeneration (2 papers, 2021 to 2022). Degeneration of the retina. "Here we have shown that FoxP3 is expressed in the aged retina and under circumstances of retinal degeneration as well as in acute and chronic inflammation in various species including humans." (PMID 36273134, 2022). "Additionally, our current data indicate that iMSC can enhance differentiation of T cells into Foxp3 Tregs in vitro and therapeutically improve the retina’s immune function by upregulation of Tregs to decrease inflammation and reduce I/R injury-induced retinal degeneration in vivo." (PMID 34831229, 2021). "Eye tissue from humans, mouse models of retinal degeneration and rats, and ARPE-19, a human RPE cell line for in vitro experiments, underwent immunohistochemical, immunofluorescence staining, and PCR or immunoblot analysis to determine the intracellular localization and phosphorylation of FoxP3." (PMID 36273134, 2022).
Rotavirus infection (2 papers, 2022). Infection with any of the rotaviruses. "These cells could indeed drive distinct outcomes during rotavirus infection compared to their FOXP3+ Treg counterparts." (PMID 35336866, 2022).
RSV bronchiolitis (2 papers, 2020 to 2023). "The slight reduction in both Treg (CD4+CD25hiFoxp3hi) and activated CD4+CD25+Foxp3+ T cells could be due to a recruitment of these cells to airway, apoptosis or their plasticity in these children with acute severe RSV bronchiolitis." (PMID 31901157, 2020). "The purpose of this study was to evaluate a putative relationship between circulating Foxp3+ Tregs and cytokine production of in vitro activated CD4+ T cells in infants with acute severe RSV bronchiolitis and the development of recurrent wheezing in the first 3 years of life." (PMID 31901157, 2020). "Levels of circulating FOXP3 mRNA and the counts of FOXP3+ CD4+ regulatory T cells, which encompass both suppressive resting Treg cells (CD45RA+ FOXP3lo) and suppressive activated Treg cells (CD45RA+ FOXP3hi), are diminished in infants who are hospitalized due to RSV bronchiolitis." (PMID 37764926, 2023).
schwannoma (2 papers, 2019 to 2024). A benign, usually encapsulated slow growing tumor composed of Schwann cells. "In NF2 patients, the number of Foxp3-positive cells in schwannomas with a progressive course was significantly higher than in those without a progressive course, suggesting that growth may be associated with Foxp3-positive regulatory T cells (Tregs)." (PMID 31848332, 2019). "In patients with NF2, the abundance of Foxp3-positive regulatory T cells in progressing schwannomas significantly exceeded that in non-progressing cases, indicating a potential link between the presence of these cells and tumor growth." (PMID 38817895, 2024).
scleroderma (2 papers, 2020 to 2022). Scleroderma is a rare autoimmune connective tissue disorder characterized by abnormal hardening of the skin and, sometimes, other organs. "In addition, a study by Wanget al. in a scleroderma model has also shown the ability of intraperitoneal metformin to dose dependently reduce IL-17A levels and RORγt expression and increase FOXP3 mRNA expression." (PMID 34386197, 2020). "Additional experiments regarding epigenetic factors of FoxP3 stability as well as changes at the transcriptome level as performed in scleroderma would have been interesting to assess but were not possible due to relatively low cell counts in volume-restricted blood samples in JIA patients." (PMID 35410224, 2022).
small intestinal tumors (2 papers, 2011 to 2015). "Wild type Foxp3+ splenic Tregs potently decreased both large (89%) and small intestinal tumors (54%)." (PMID 26146642, 2015). "However, immunohistochemical characterization of small intestinal tumors from PKA antagonist Rp-8-Br-cAMPS treated animals did not reveal any significant changes in the number of CD3+ T cells, CD8+ cytotoxic T cells, Foxp3+ Tregs or CD56+ natural killer (NK) cells." (PMID 22168384, 2011).
tauopathy (2 papers, 2021 to 2024). Neurodegenerative disorders involving deposition of abnormal tau protein isoforms (tau proteins) in neurons and glial cells in the brain. "Here, we hypothesized that the brain-immune communication pathway that is needed to be activated to combat tauopathy involves monocyte mobilization via the C-C chemokine receptor 2 (CCR2)/CCL2 axis, and additional immune cells, such as CD4+ T cells, including FOXP3+ regulatory CD4+ T cells." (PMID 34172073, 2021).
tongue tumor (2 papers, 2019 to 2021). "A low stromal CD8+/FOXP3+ ratio was significantly associated with a better prognosis in patients with female gender (p = 0.009), history of alcohol consumption (p = 0.03), tongue tumor location (p = 0.01) and well-differentiated tumors (p = 0.03)." (PMID 34201050, 2021). "Furthermore, we observed that supplementing α-PD-1 + α-CTLA-4 treatment with STING agonist administration into the flank tumors was associated with a decrease in the frequencies of CD4+Foxp3+ Treg as well as of MDSC expressing Arginase 1 in both flank and tongue tumors." (PMID 31533840, 2019).
Tonsillar Cancer (2 papers, 2012 to 2020). "For patients with tonsillar cancer, a high CD8/Foxp3+ ratio positively correlated with DFS." (PMID 32758195, 2020).
uterine sarcomas (2 papers, 2021 to 2023). "Polo-like kinase 4 (PLK4), Secreted Protein, Acidic and Rich in Cysteine (SPARC) Related Modular Calcium Binding 2 (SMOC2), Special AT-rich Sequence-Binding protein 2 (SATB2), or Forkhead box P3 (FOXP3) + T cells have all been suggested as prognostic indicators for uterine sarcomas." (PMID 37173887, 2023). "The current knowledge of FOXP3+ cell function in uterine sarcomas is limited." (PMID 34799669, 2021). "As these non-Treg FOXP3+ cells lack the expression of CD45RA, including this marker for further characterization of this cell population may shed light on the function of FOXP3+ cells in uterine sarcomas and other tumors." (PMID 34799669, 2021).
abdominal aortic aneurysm (1 paper, 2018). Enlargement and ballooning of the vessel that supplies arterial blood to the abdomen, pelvis and legs. "Immunohistochemical analysis showed reduced accumulation of macrophages and increased numbers of Foxp3+ Treg in aneurysmal tissues, suggesting that expansion of Tregs may suppress local inflammation in the vessel wall and provide protection against abdominal aortic aneurysm formation." (PMID 30524295, 2018).
abscess (1 paper, 2025). An inflammatory process characterized by the accumulation of pus within a newly formed tissue cavity which is the result of a bacterial, fungal, or parasitic infection or the presence of a foreign body. "This environment may in turn drive the differentiation of FOXP3+ Tregs within the abscess collar." (PMID 39882906, 2025).
Achalasia (1 paper, 2024). A disorder of esophageal motility characterized by the inability of the lower esophageal sphincter to relax during swallowing and by inadequate or lacking peristalsis in the lower half of the body of the esophagus. "Patients with achalasia had increased circulating CD4+ T cells, CD25- T cells, CD161+ T cells, FOXP3+ Tregs, IDO-expressing regulatory plasmacytoid dendritic cells (pDCregs), and IL-10-expressing regulatory B cells (Bregs) compared to healthy individuals." (PMID 38267468, 2024).
acute leukemia (1 paper, 2019). A clonal (malignant) hematopoietic disorder with an acute onset, affecting the bone marrow and the peripheral blood. "According to the analyzed literature, only a few research groups were able to fully evaluate the percentage of Treg cells in the peripheral blood of patients with acute leukemia based on the most appropriate phenotype—CD4+CD25highCD127low/-FoxP3+ T cells." (PMID 30944830, 2019).
Aden (1 paper, 2021). "CCL17 and CCL22 within tumors are known to be associated with an increased population of Foxp3+ Tregs; thus, the high expression of these 2 chemokines may contribute to the infiltration of Tregs into patients with Aden, thereby making the tumor microenvironment more immune suppressive." (PMID 34459571, 2021).
adenomyosis (1 paper, 2025). The growth of endometrial tissue inside the muscular wall of the uterine corpus. "Future studies should include FoxP3+ cell quantification to determine whether Treg deficiency contributes to the skewing toward CD4+ and CD8+ effector phenotypes observed in our adenomyosis model." (PMID 41298316, 2025).
asthenia (1 paper, 2023). Clinical sign or symptom manifested as debility, or lack or loss of strength and energy. "The toxicity analysis by subtypes showed that the ABCC1 rs2238476-AG genotype (AG vs. GG: OR = 8.10; 95% CI = 1.69–46.63; p = 0.011) and FOXP3 rs376154-GT genotype (OR = 4.11; 95% CI = 1.22–15.30; p = 0.027) were associated with the appearance of asthenia." (PMID 37761008, 2023). "Moreover, a tendency was found toward an association between the FOXP3 rs3761548-GT and GG genotypes and asthenia during MTX therapy (GT vs. TT/GG: OR = 3.25, 95% CI = 1.14–9.79; GG vs. TT/GT: OR = 1.12, 95% CI = 0.35–3.53, p = 0.051)." (PMID 37761008, 2023). "In the multivariate analysis, it was observed that patients carrying the FOXP3 rs376154-GT and GG genotypes showed a higher risk of developing adverse events after the administration of MTX, specifically asthenia." (PMID 37761008, 2023).
autism spectrum disorder (1 paper, 2022). A spectrum of developmental disorders that includes autism, and Asperger syndrome. "The researchers tried to find an association between FOXP3 gene polymorphisms (rs3761548 and rs2232365) and an autism spectrum disorder." (PMID 35641708, 2022).
auto-inflammatory syndrome (1 paper, 2019). "Male Malt1fl/fl;FIC or female Malt1fl/fl;FIC/FIC mice develop a lethal auto-inflammatory syndrome with a massive pathological activation of Tconv and B cells with the same kinetics and severity compared to Bcl10fl/fl;FIC mice or FoxP3-deficient scurfy mice." (PMID 31138793, 2019).
autoimmune cardiomyopathy (1 paper, 2021). An autoimmune form of cardiomyopathy. "Multiple reports have demonstrated that the decrease of Treg specifically expressing Foxp3 may lead to reduced autoimmune tolerance and autoimmune cardiomyopathy." (PMID 34669781, 2021).
Azoospermia (1 paper, 2019). Absence of any measurable level of sperm,whereby spermatozoa cannot be observed even after centrifugation of the semen pellet. "This study was designed to identify novel pathogenic variants of FOXP3 gene causing azoospermia." (PMID 31855573, 2019). "FOXP3 protein was expressed at a lower level or undetected in spermatocytes of mutant testis of non-obstructive azoospermia patients compared to obstructive azoospermia patients." (PMID 31855573, 2019). "We have identified two new pathogenic variants of FOXP3 in non-obstructive azoospermia patients with high incidence, and FOXP3 silencing inhibits the proliferation and enhances the apoptosis of human spermatogonial stem cells." (PMID 31855573, 2019). "In this study, we identified two types of PV of FOXP3 (GenBank: NM_014009.3) in a large cohort of patients with non-obstructive azoospermia (NOA)." (PMID 31855573, 2019).
B-cell acute lymphoblastic leukemia (1 paper, 2014). A neoplasm of lymphoblasts committed to the B-cell lineage, typically composed of small to medium-sized blast cells. "However, activin A also contributes to the switching of CD4+CD25-Foxp3- (Foxp3: forkhead box P3) cells to CD4+CD25+Foxp3+ T-regulatory (Treg) cells, which correlates with immunosuppression in patients with B-cell acute lymphoblastic leukemia." (PMID 25560921, 2014).
basal cell carcinoma (1 paper, 2021). A carcinoma involving the basal cells. "CD4+CD25+Foxp3+ T-cells can be found intermingled with human basal cell carcinoma along with the TH2 cytokines IL-4 and IL-10." (PMID 34771569, 2021).
benign neurofibroma (1 paper, 2017). "MPNST tumors overall displayed comparatively low FOXP3+ cell counts, similar to those observed in the nodular and plexiform benign neurofibroma groups." (PMID 29137242, 2017).
brain cancer (1 paper, 2017). A primary or metastatic malignant neoplasm affecting the brain. "We observed greatly enhanced FOXP3 induction in the presence of supernatants from colon, lung and liver, but not brain cancer cells over that observed in their absence." (PMID 28239749, 2017).
brain inflammation (1 paper, 2023). "Cerebral Tregs-Foxp3 inhibits LPS-induced microglial reactivity and brain inflammation via IL-10, IL-35, CTLA4, and CD39 response pathways, suggesting immuno-surveillance and immunomodulatory roles of the gut-brain microglia Tregs-Foxp3 pathway in maintaining cerebral homeostasis." (PMID 37256150, 2023).
cardiomyopathy (1 paper, 2012). A disease of the heart muscle or myocardium proper. "We next aimed to study if the reduced frequency of CD4+CD25+ T cell expressing CTLA-4 and Foxp3 that we found in severe cardiomyopathy patients correlated with deficient regulatory activities." (PMID 22545173, 2012). "Free/mild cardiomyopathy patients presented higher frequency of CD4+CD25high T cells expressing Foxp3 (P = 0.033) and CTLA-4 (P = 0.042) than moderate/severe cardiomyopathy patients." (PMID 22545173, 2012). "A higher expression of CTLA-4 and Foxp3 in the CD4+CD25high T cells from free/mild cardiomyopathy patients was observed, when compared to moderate/severe cardiomyopathy patients." (PMID 22545173, 2012). "The high amount of CD4+CD25+ T cells expressing CTLA-4 and Foxp3 (that activate the regulatory T cell machinery) in CD4+ CD25+ T cells of free/mild cardiomyopathy and Bz treated patients may be related to high suppressor activity of these cells." (PMID 22545173, 2012). "Therefore, more IL-17 and Foxp3 expression is preferentially found in free/mild cardiomyopathy patients." (PMID 22545173, 2012). "High percentage of CD4+CD25+Low T cells expressing Foxp3 (P = 0.016) and CTLA-4 (P = 0.046) were also observed in free/mild cardiomyopathy patients compared with moderate severe cardiomyopathy patients." (PMID 22545173, 2012). "The impairment in suppressive activity observed in CD4+CD25+ T cells from patients suffering from severe cardiomyopathy correlates with the observation of reduced amounts of CD4+CD25+ T cells expressing CTLA-4 and Foxp3 in this group of patients." (PMID 22545173, 2012). "The mechanism leading to reduced expression of Foxp3 and CTLA-4 and consequently, deficient suppressive activity of CD4+CD25+ T cells from patients with cardiomyopathy has not been elucidated." (PMID 22545173, 2012). "Interestingly, the expression of CTLA-4, but not CD103, GITR and Foxp3, in CD4+CD25high T cells was decreased in moderate/severe cardiomyopathy compared with free/mild cardiomyopathy patients and health individuals." (PMID 22545173, 2012).
cardiotoxicity (1 paper, 2025). Toxicity that impairs or damages the heart. "Those with cardiotoxicity had a noticeable increase in circulating CD4 + FOXP3 + and CD8 + PRF1 + T cells at disease onset." (PMID 41510228, 2025).